Y_RNA (Y RNA )
Gene: Miscellaneous RNA gene on chromosome 1 (148,330,271 to 148,330,394, forward strand). Ensembl gene ENSG00000252744.
Homologues: Orthologues: chimpanzee Y_RNA (84% identical). Paralogues in human: Y_RNA (69% identical), Y_RNA (66% identical), Y_RNA (65% identical), RNY3 (65% identical), RNY3P1 (64% identical), Y_RNA (64% identical), RNY3P4 (63% identical), Y_RNA (63% identical), Y_RNA (62% identical), RNY3P11 (61% identical), Y_RNA (61% identical), RNY3P12 (60% identical), and 82 more.